ENSG00000260861 (novel protein, SIRPB1-SIRPD readthrough)
Gene: Protein-coding gene on chromosome 20 (1,540,144 to 1,620,009, reverse strand). Ensembl gene ENSG00000260861.
Genetic constraint (gnomAD): Loss-of-function variants: 6 observed, 11.63 expected, observed/expected ratio (o/e) 0.52, 90% interval 0.28 to 1.02. Missense variants: 202 observed, 214.23 expected, observed/expected ratio (o/e) 0.94, 90% interval 0.84 to 1.06. Synonymous variants: 88 observed, 83.19 expected, observed/expected ratio (o/e) 1.06, 90% interval 0.89 to 1.26.